SOS1 (SOS Ras/Rac guanine nucleotide exchange factor 1)
Description:
Promotes the exchange of Ras-bound GDP by GTP. Probably by promoting Ras activation, regulates phosphorylation of MAP kinase MAPK3/ERK1 in response to EGF. Catalytic component of a trimeric complex that participates in transduction of signals from Ras to Rac by promoting the Rac-specific guanine nucleotide exchange factor (GEF) activity (By similarity).
Synonyms: SOS-1; HGF; GF1; GGF1; GINGF; NS4
Tractability: Small molecule: a structure with a bound ligand is known; a high-quality ligand is known; it has a high-quality binding pocket. Antibody: its Gene Ontology location is reachable by antibodies, with high confidence. PROTAC: ubiquitination databases record sites on it; its protein half-life has been measured; a small molecule that binds it is known.
Chemical probes: BAY-293 (high quality), BI-3406 (high quality), MRTX0902 (high quality), SOS1-IN-1-15 (high quality), VUBI1 (high quality)
Gene: Protein-coding gene on chromosome 2 (38,962,206 to 39,124,345, reverse strand). Ensembl gene ENSG00000115904.
Subcellular location (Human Protein Atlas): Cytosol
Pathways (Reactome):
Signal Transduction: Activated NTRK2 signals through FRS2 and FRS3; Activated NTRK2 signals through RAS; Activated NTRK3 signals through RAS; Downstream signal transduction; EGFR Transactivation by Gastrin; Erythropoietin activates RAS; FRS-mediated FGFR1 signaling; FRS-mediated FGFR2 signaling; FRS-mediated FGFR3 signaling; FRS-mediated FGFR4 signaling; G alpha (12/13) signalling events; GRB2 events in EGFR signaling; GRB2 events in ERBB2 signaling; GRB2:SOS provides linkage to MAPK signaling for Integrins; Insulin receptor signalling cascade; MET activates RAS signaling; NRAGE signals death through JNK; RAC1 GTPase cycle; RAF/MAP kinase cascade; Regulation of KIT signaling; SHC-mediated cascade:FGFR1; SHC-mediated cascade:FGFR2; SHC-mediated cascade:FGFR3; SHC-mediated cascade:FGFR4; SHC-related events triggered by IGF1R; SHC1 events in EGFR signaling; SHC1 events in ERBB2 signaling; SHC1 events in ERBB4 signaling; SOS-mediated signalling; Signal attenuation; Signaling by LTK; Signaling by SCF-KIT; Signalling to RAS
Disease: Constitutive Signaling by EGFRvIII; Constitutive Signaling by Ligand-Responsive EGFR Cancer Variants; Constitutive Signaling by Overexpressed ERBB2; Potential therapeutics for SARS; Signaling by ERBB2 ECD mutants; Signaling by ERBB2 KD Mutants; Signaling by ERBB2 TMD/JMD mutants
and 22 more pathways
Gene Ontology:
Molecular function: guanyl-nucleotide exchange factor activity; molecular condensate scaffold activity; protein binding; GTPase activator activity; epidermal growth factor receptor binding; protein heterodimerization activity; protein kinase binding; SH3 domain binding
Biological process: epidermal growth factor receptor signaling pathway; Ras protein signal transduction; regulation of cell population proliferation; regulation of transcription by RNA polymerase II; T cell activation; axon guidance; cytokine-mediated signaling pathway; Fc-epsilon receptor signaling pathway; leukocyte migration; positive regulation of Rac protein signal transduction; signal transduction; B cell receptor signaling pathway; insulin receptor signaling pathway; insulin-like growth factor receptor signaling pathway; myelination; neurotrophin TRK receptor signaling pathway; positive regulation of epidermal growth factor receptor signaling pathway; positive regulation of small GTPase mediated signal transduction; response to ischemia; Schwann cell development; small GTPase-mediated signal transduction
Cellular component: cytoplasm; GTPase complex; cytosol; plasma membrane; glutamatergic synapse; neuronal cell body; postsynaptic density
Genetic constraint (gnomAD): Loss-of-function variants: 13 observed, 71.79 expected, observed/expected ratio (o/e) 0.18, 90% interval 0.12 to 0.29. The upper end of that interval is the gene's LOEUF score, 0.29, which puts it in group 1 of 6, group 1 being the genes least tolerant of losing a copy. Missense variants: 750 observed, 947.52 expected, observed/expected ratio (o/e) 0.79, 90% interval 0.75 to 0.84. Synonymous variants: 306 observed, 324.67 expected, observed/expected ratio (o/e) 0.94, 90% interval 0.86 to 1.04.
Gene-disease validity (ClinGen):
ClinGen rates the evidence that SOS1 causes each of these diseases.
Noonan syndrome (autosomal dominant): Definitive. Noonan Syndrome (NS) is characterized by short stature, typical facial dysmorphism and congenital heart defects.
cardiofaciocutaneous syndrome (autosomal dominant): Disputed. Cardiofaciocutaneous (CFC) syndrome is a RASopathy characterized by craniofacial dysmorphology, congenital heart disease, dermatological abnormalities (most commonly hyperkeratotic skin and sparse, curly hair), growth retardation and intellectual disability.
Costello syndrome (autosomal dominant): Disputed. Costello syndrome (CS) is a rare multisystemic disorder characterized by failure to thrive, short stature, developmental delay or intellectual disability, joint laxity, soft skin, and distinctive facial features.
Cancer hallmarks: proliferative signalling (promotes); invasion and metastasis (promotes); tumour promoting inflammation; change of cellular energetics
Homologues: Orthologues: chimpanzee SOS1 (99% identical), dog SOS1 (99% identical), pig SOS1 (99% identical), macaque SOS1 (98% identical), rabbit SOS1 (97% identical), mouse Sos1 (97% identical), rat Sos1 (97% identical), guinea pig SOS1 (95% identical), tropical clawed frog sos1 (88% identical), zebrafish sos1 (44% identical). Paralogues in human: SOS2 (70% identical), RAPGEF2 (19% identical), RAPGEF6 (17% identical), RASGRF1 (14% identical), RASGRF2 (14% identical), RAPGEF1 (12% identical), RASGRP1 (10% identical), RASGRP3 (10% identical), RAPGEF3 (9% identical), RAPGEF4 (9% identical), RASGRP4 (9% identical), RALGDS (9% identical), and 12 more.
Diseases named in the same sentence as SOS1 in open-access papers:
SOS1 is named in the same sentence as 168 diseases in open-access papers, as found by Europe PMC text mining. Sharing a sentence is not in itself a finding about the gene and the disease. The quoted sentences say what the papers report.
Noonan syndrome (67 papers, 2011 to 2025). "Structural studies revealed that Noonan syndrome‐associated mutations (e.g., E108K) relieve Sos1 autoinhibition, offering new perspectives for understanding disease mechanisms and drug development." (PMID 41020039, 2025). "In comparison to global trends, our cohort showed a notably high proportion of Noonan syndrome (NS) cases attributed to pathogenic variants in SOS1 and RAF1, with each accounting for 16% of cases." (PMID 41292581, 2025). "Subsequently, trametinib was used to treat an individual with Noonan syndrome caused by a SOS1 variant (SOS1–Noonan syndrome) and CCLA manifesting as protein-losing enteropathy." (PMID 38618951, 2024). "Rarely, germline mutations in PTPN11, encoding the phosphatase SHP2, and in SOS1, encoding the guanine nucleotide exchange factor SOS1, have been observed in patients with Noonan syndrome, who subsequently developed ALL." (PMID 35294722, 2022). "Missense pathogenetic variants of SOS1 gene are the second most common cause of Noonan syndrome (NS) and account approximately for 13% to 17% of cases." (PMID 35986401, 2022). "The second most-frequent genetic lesions found in patients with Noonan syndrome are mutations in the RAS-GEF SOS1, which abrogate the SOS1 autoinhibitory function and result in its constitutive activation." (PMID 35234863, 2022). "A further child with Noonan syndrome due to a de novo mutation in SOS1 and a severe lymphatic disorder was also successfully treated with trametinib." (PMID 36238151, 2022). "In the last family of 3 siblings with similar 46, XY DSD phenotypes (DSD cases 52, 53and 82), a heterozygous splice site variant of uncertain significance (c.3347-1G > A) in SOS1 gene (Noonan syndrome 4; MIM 610733) was identified in the sister (DSD 82)." (PMID 36110220, 2022). "For example, studies of Noonan Syndrome-associated cardiac defects reveal that hypertrophic cardiomyopathy is observed in less than 20% of cases linked to PTPN11/SHP2 or SOS1 mutations, but greater than 90% of RAF1 mutations." (PMID 31017896, 2019). "The PTPN11 gene is the most implicated gene in Noonan syndrome (61%), followed by SOS1 and RAF1 genes (15 and 6%, respectively)." (PMID 31030682, 2019). "The assay identified p.A72G, p.I282V, and p.P491S variants of the PTPN11 gene and a p.I437T variant of the SOS1 gene in 4 cases with Noonan syndrome." (PMID 30541462, 2018). "About 10% of Noonan syndrome patients have SOS1 mutations that are thought to confer hyperactivity of SOS1." (PMID 28386265, 2017). "This analysis identified activating SOS1 mutations associated with Noonan syndrome as significantly altered in melanoma and the first kinase-activating mutations in ACVR1 associated with adult tumors." (PMID 27304678, 2016). "Grb2 and Sos1 function interdependently on each other, thus, mutations on Sos1 or unusual phosphorylation on Grb2 would lead to aberrant physiological events such as Noonan syndrome and tumorigenesis." (PMID 24775912, 2014). "SOS1 mutations have recently been reported to occur in Noonan’s syndrome and Hereditary Gingival Fibromastosis Type 1 disease, both of which are associated with abnormal Ras activation." (PMID 22761938, 2012). "Later, mutations of the PTPN11 gene and the SOS1 gene were identified in patients with Noonan syndrome." (PMID 22640403, 2012). "The following whole exome sequencing ruled out any compound heterozygosity and revealed a heterozygous pathogenic variation in the SOS1 gene (NM_005633.4:c.1644T>A, p.Ser548Arg) that confirmed Noonan syndrome 4 (Phenotype MIM number: 610733, location: 2p22.1, Gene/Locus MIM number: 182530)." (PMID 40507736, 2025). "A SOS1 c.1132A>G variant was inherited from a father with Noonan syndrome." (PMID 36959127, 2023). "SOS1 heterozygous gain-of-function mutations are correlated with Noonan syndrome 4 (OMIM: 610733)." (PMID 35806420, 2022).
Noonan syndrome (continued). "In this regard, gain-of-function mutations of Sos1/2 have been reported in RASopathies, particularly in patients with Noonan syndrome, who may develop skin abnormalities as well as granular skin tumors." (PMID 33946974, 2021). "Rare pathogenic variants in the PTPN11, KRAS, SOS1 and RAF1 genes are the main molecular causes of Noonan syndrome (NS)." (PMID 40041314, 2025). "Noonan syndrome is a RASopathy caused predominantly by genetic variants encoding the SHP2 protein (e.g., PTPN11, SOS1, RAF1), ultimately leading to hyperactivation of the RAS-MAPK pathway." (PMID 41001496, 2025). "We present two cases of Noonan syndrome with external hydrocephalus in the second trimester in the presence of the variations of the SOS1 and PTPN11 genes." (PMID 40507736, 2025). "RasGEFs (e.g., Sos1/2, RasGRF1/2, and RasGRP1‐4) primarily regulate the MAPK signaling pathway and cell proliferation/differentiation, with their mutations linked to Noonan syndrome and leukemia." (PMID 41020039, 2025). "In another case series, three infants with Noonan syndrome (SOS1, RIT1, PTPN11) all had a reduction in chylous effusions, chylous ascites, and improvement in respiratory status with trametinib therapy." (PMID 38618951, 2024). "In an infant with SOS1–Noonan syndrome and pulmonary lymphangiectasia and pleural effusions requiring invasive ventilation, trametinib treatment resulted in resolution of the effusions within 1 week and transition to room air after 3 weeks." (PMID 38618951, 2024). "Unexpected finding was observed in SOS1 and RAF1 genes which are both reported to be associated with 10–20% of Noonan syndrome cases, and were observed at lower detection rate of 6% each in the current study." (PMID 37815686, 2024). "In mice, expression of a KRAS(V14I), SOS1(E846K), or RIT1(A57G) mutation produces many Noonan syndrome-related phenotypes, like growth delay, craniofacial abnormalities, and cardiac defects." (PMID 38463630, 2024). "Mutations associated with Noonan syndrome alone include CBL, BRAF, KRAS, LZTR1, MAP2K1 (MEK1), NRAS, PTPN11, RAF1, RIT1, SOS1 and SOS2." (PMID 38550930, 2023). "Mutations in 16 genes, including PTPN11 (50%), SOS1 (20%) and RAF1 (5%–15%), have been linked to the development of Noonan syndrome." (PMID 37525886, 2023). "SOS1 and BRAF are associated with Noonan syndrome, an autosomal‐dominant disorder characterized by short stature, congenital heart disease, curly hair, and facial dysmorphia." (PMID 35505885, 2022). "A previous study found that SOS2 was homologous to SOS1, the second gene frequently related to Noonan syndrome." (PMID 35141295, 2021). "Individuals with Noonan Syndrome (MIM: 163950) comprise ~50% of all RASopathy cases and mutations have been observed in multiple genes, including PTPN11/SHP2, SOS1, SHOC2, KRAS, NRAS, LZTR1 (MIM: 600574), RAF1/CRAF, and MAP2K1/MEK1." (PMID 31017896, 2019). "Pathogenic gain-of-function variants in RAF1—among other genes including PTPN11, SOS1, and KRAS—cause Noonan syndrome." (PMID 30597917, 2018). "The group included four patients with Noonan syndrome, three with heterozygous mutations of the PTPN11 gene, and one with an SOS1 mutation." (PMID 30541462, 2018). "SOS1 and KRAS, but not SOS2, have been implicated in human rasopathies, including mutations in SOS1 and KRAS in Noonan syndrome and KRAS mutations in cardiofaciocutaneous syndrome." (PMID 23761422, 2013). "While the phenotypes of many mutant mouse models correlate with human patients, the discrepancies with Raf1, SOS1, or other genes suggest more information is needed to understand how these genes influence Noonan syndrome phenotypes and how the pathway as a whole regulates nervous system function." (PMID 38463630, 2024). "SOS1 is a Ras GEF, which is overactivated by mutations associated with Noonan syndrome." (PMID 38463630, 2024).
Noonan syndrome (continued). "In addition to the PTPN11 mutations in the RAS‐MAPK signaling pathway, including KRAS, SOS1, RAF1, SHOC2, NRAS, BRAF and CBL, can also cause Noonan syndrome." (PMID 37525886, 2023). "Mutations in the following genes that cause Noonan syndrome have been identified: RAS family GTPase proteins (KRAS, NRAS, RIT1, and RRAS), RAS signal function modulators (PTPN11, SOS1, SOS2, CBL, RASA2, and SHOCS2), and downstream signal transducers (RAF1 and BRAF)." (PMID 38248880, 2023). "SOS1 is a guanine nucleotide exchange factor (GEF) which interacts with RAS proteins, involved in the transduction of signals that control cell growth and differentiation (also associated with Noonan syndrome)." (PMID 34208491, 2021). "Meanwhile, prolonged activation of PI3K/AKT and ERK signaling disrupts the regulation of cell growth and division, leading to the characteristic features of Noonan syndrome (OMIM# 163950) that is caused by germline variation in KRAS genes (PTPN11, SOS1, RAF1, LZTR1, etc.)." (PMID 31752936, 2019). "Both SOS1 and INPPL1 are associated with growth disorders – Noonan syndrome and opsismodysplasia." (PMID 27651465, 2016). "In addition, we verified by exomeanalysis that the patient did not have any pathogenic variants in the genes associatedwith Noonan Syndrome and other rasopathies (PTPN11,SHOC2, KRAS, CBL,SOS1, RAF1, HRAS,NRAS, RASA1, SPRED1,BRAF, MAP2K1, MAP2K2, RIT1 andRRAS)." (PMID 27561113, 2016). "In the absence of SH3BP2 mutation in an individual considered to have Cherubism, genetic screening for mutations in genes implicated in Noonan syndrome (PTPN11, SOS1, RAF1, KRAS, NRAS, and BRAF), NF1, and craniofacial cutaneous syndrome (BRAF, MAP2K1) should be undertaken." (PMID 25409853, 2014). "A small proportion of individuals with Noonan syndrome also exhibit multiple gnathic GCG previously reported as Noonan-like/multiple GCG, but this phenotype is now recognized to be allelic with Noonan syndrome, as mutations in PTPN11, SOS1, and RAF1 have been reported in this syndrome." (PMID 25409853, 2014). "Interestingly, the remaining genes found to result in the clinical features of Noonan syndrome also involve the Ras-MAP kinase signaling system, including mutations in KRAS, SOS1 and RAF1." (PMID 22011734, 2011). "Noonan syndrome is a cluster of monogenic conditions involving several genes in the RAS-MAPK pathway (PTPN11, SOS1, SHOC2, MAP2K1/2 and KRAS in the included paper)." (PMID 36729042, 2023). "Over the years, several other genes involved in Noonan syndrome (KRAS, SOS1, RAF1, MAP2K1, BRAF, NRAS, RIT1, and LZTR1) have been identified, acting at different levels of the RAS-mitogen-activated protein kinase pathway." (PMID 38254922, 2023). "Secondary screening confirmed the enhanced sensitivity of RIT1-mutant cells to depletion of USP9X and AURKA along with the RAS pathway and Noonan syndrome genes SHOC2 and SOS1." (PMID 34373451, 2021).